BOLA2 (bolA family member 2)
Description:
Acts as a cytosolic iron-sulfur (Fe-S) cluster assembly factor that facilitates [2Fe-2S] cluster insertion into a subset of cytosolic proteins. Acts together with the monothiol glutaredoxin GLRX3.
Synonyms: BOLA2A; My016
Gene: Protein-coding gene on chromosome 16 (29,453,588 to 29,455,012, reverse strand). Ensembl gene ENSG00000183336.
Subcellular location: Cytoplasm; Nucleus
Pathways (Reactome):
Immune System: Gene and protein expression by JAK-STAT signaling after Interleukin-12 stimulation
Gene Ontology:
Molecular function: protein binding; iron-sulfur cluster binding; 2 iron, 2 sulfur cluster binding
Biological process: [2Fe-2S] cluster assembly; cell redox homeostasis; intracellular iron ion homeostasis; iron-sulfur cluster assembly; protein maturation
Cellular component: cytoplasm; iron-sulfur cluster assembly complex; nucleus; cytosol
Homologues: Orthologues: chimpanzee BOLA2B (98% identical), macaque BOLA2B (98% identical), dog BOLA2B (93% identical), pig BOLA2B (91% identical), rat Bola2 (88% identical), rat Bola2-ps1 (88% identical), guinea pig Bola2b (87% identical), mouse Bola2 (87% identical), rat AABR07034928.1 (78% identical), tropical clawed frog bola2 (76% identical), zebrafish BOLA2B (58% identical), Drosophila melanogaster CG33672 (47% identical). Paralogues in human: BOLA2B (100% identical), BOLA1 (43% identical), BOLA3 (26% identical).
Diseases named in the same sentence as BOLA2 in open-access papers:
BOLA2 is named in the same sentence as 10 diseases in open-access papers, as found by Europe PMC text mining. Sharing a sentence is not in itself a finding about the gene and the disease. The quoted sentences say what the papers report.
anaemia (3 papers, 2022 to 2024). "Analysis of phenotypes associated with BOLA2 copy-number variation revealed reduced BOLA2 dosage associated with mild anaemia while, inversely, increased BOLA2 dosage improves systemic iron homeostasis." (PMID 38919062, 2024). "A recent study has shown that low CNVs of BolA2 might contribute to iron-deficiency anemia." (PMID 36923798, 2023).
hepatocellular carcinoma (2 papers, 2019 to 2023). A malignant tumor that arises from hepatocytes. "Regarding cancer research, BolA2 was found highly expressed in hepatocellular carcinoma." (PMID 36923798, 2023).
iron deficiency (2 papers, 2023 to 2024). "In line, mice lacking BOLA2 show early evidence of iron deficiency." (PMID 38919062, 2024).
ovarian carcinoma (2 papers, 2021 to 2023). A malignant neoplasm originating from the surface ovarian epithelium. "The elevated expression of BolA1, BolA2, and BolA3 was significantly associated with the prognosis of ovarian cancer patients." (PMID 36923798, 2023). "In cancer, BolA2 and BolA3 were expressed at higher levels in ovarian cancer than in the normal adjacent tissue." (PMID 36923798, 2023). "Concerning BOLA2, the mRNA expressions were higher in some kinds of ovarian cancer tissues in Lu′s dataset." (PMID 34078439, 2021). "The mRNA and protein expression levels of BOLA2 and BOLA3 were heavily higher in ovarian cancer tissues than in normal ovarian tissues." (PMID 34078439, 2021).
breast carcinoma (1 paper, 2025). "The role of the BOLA2 gene in the carcinogenesis of breast cancer cells, as well as the underlying mechanism, remains poorly understood." (PMID 41465298, 2025). "Furthermore, elevated SM4 levels on breast cancer cells modulates the transcription of the BOLA2 gene, which is implicated in apoptotic processes, via the integrin β1/STAT5 signaling pathway." (PMID 41465298, 2025). "In this proposal, STAT5 was identified as a key regulatory protein driving the overexpression of BOLA2 in breast cancer cells exhibiting a malignant, mesenchymal-like phenotype." (PMID 41465298, 2025). "Based on these results, an in silico analysis was performed to identify potential transcription factor binding sites that could affect BOLA2 promoter activity in breast cancer cells." (PMID 41465298, 2025). "Using MDA-MB-231 and MDA-MB-468 breast cancer cells with altered CST/SM4 levels, RNA sequencing and functional analyses revealed that overproduction of the CST/SM4 significantly downregulated BOLA2, a gene in the CIAPIN1 pathway involved in apoptosis." (PMID 41465298, 2025).
lymphopenia (1 paper, 2022). Reduction in the number of lymphocytes. "As both neutropenic probands had the lowest copy number of the BOLA2 duplicon (i.e. three copies), we assessed a possible association between the neutropenia/lymphopenia and the duplicon copy number." (PMID 35715439, 2022).
neutropenia (1 paper, 2022). A decrease in the number of neutrophils found in the blood. "We found a trend between lower copy number of the BOLA2 duplicon and higher susceptibility to moderate neutropenia among 16p11.2 deletion carriers." (PMID 35715439, 2022). "There is a trend between 16p11.2 deletion with lower copy-number of the BOLA2 duplicon and higher susceptibility to moderate neutropenia." (PMID 35715439, 2022).
cancer (3 papers, 2019 to 2023). A tumor composed of atypical neoplastic, often pleomorphic cells that invade other tissues. "In the Hep3b cell line, knockdown of BOLA2B reduced the level of iron staining, indicating that BolA2 plays a key role in iron homeostasis in cancer cells." (PMID 36923798, 2023). "We performed a pan-cancer analysis of the expression of BOLA2 genes in normal and cancerous tissues by using the Oncomine database and found that BOLA2 was increased in most types of solid tumors, including breast, colorectal, pancreatic, and liver." (PMID 31413749, 2019). "In the ovarian cancer, the BOLA2 and BOLA3 were higher in cancer tissues and may act as prognostic biomarkers, and in the lung adenocarcinoma, the BOLA3 was correlated with the immune cell infiltrates." (PMID 36017386, 2022). "Although its expression was reported to be elevated during tumorigenesis, BOLA2 has not been extensively studied in cancer, including HCC." (PMID 31413749, 2019). "Thus, we could guess that BOLA2 has the ability to promote the development of HCC and maintains cancer cell growth in the condition of metabolic stress." (PMID 36017386, 2022). "Thus, we speculate that BOLA2 might promote the development of HCC and maintain cancer cell growth under metabolic stress conditions." (PMID 31413749, 2019).
tumor (2 papers, 2019 to 2022). "In this work, we performed a TIMER analysis, and the results indicated that BOLA2 is highly associated with p62 expression in the tumor immunological microenvironment." (PMID 31413749, 2019). "Furthermore, loss-of-function studies determined that BOLA2 plays critical roles in promoting iron overload, tumor growth and TH." (PMID 31413749, 2019). "The precise mechanism underlying this BOLA2-mediated TH of tumor growth remains to be determined." (PMID 31413749, 2019). "Compared to the WT group, the knockout of BOLA2 in HCC cells induced strong tumor growth suppression." (PMID 31413749, 2019). "Further studies of BOLA2 in HCCs will be of interest to clarify its precise role in tumor growth and TH." (PMID 31413749, 2019). "Collectively, the present results indicate that BOLA2 is highly expressed in tumor tissues and is significantly correlated with a poor prognosis in HCC patients." (PMID 31413749, 2019). "Next, we attempted to determine whether BOLA2 knockout had the same suppressive effects on HCC tumor growth in vivo." (PMID 31413749, 2019). "We hypothesized that BOLA2 might act as a tumor promoter to enhance HCC development." (PMID 31413749, 2019). "And yet, even the overexpression of BOLA2 is required to drive HCC tumor growth and tumor hemorrhage, and high BOLA2 can promote tumor growth and predict the HCC prognosis." (PMID 36017386, 2022). "We examined the relative transcription levels of BOLA2 by qRT-PCR in tumor tissues and corresponding nontumour tissue (NT) in a cohort of 96 HCC patients." (PMID 31413749, 2019). "The mRNA expression of BOLA2 in the HCC tumor tissues of the training cohort significantly correlated with the clinicopathological features of tumor invasion and aggression, such as venous invasion, satellite nodules, tumor hemorrhage (TH), tumor differentiation and HCC stage." (PMID 31413749, 2019).
BOLA2 also shares sentences with these, for which no sentence is quoted: psychosis (1 paper).